ENSG00000268279 (novel transcript)
Gene: Protein-coding gene on chromosome 3 (14,135,217 to 14,148,252, forward strand). Ensembl gene ENSG00000268279.
Genetic constraint (gnomAD): Missense variants: 111 observed, 108.27 expected, observed/expected ratio (o/e) 1.03, 90% interval 0.88 to 1.2. Synonymous variants: 46 observed, 40.25 expected, observed/expected ratio (o/e) 1.14, 90% interval 0.9 to 1.46.